OR5P2 (olfactory receptor family 5 subfamily P member 2)
Description:
Odorant receptor (Potential). May be involved in taste perception.
Synonyms: JCG3; JCG4
Tractability: Antibody: UniProt places it where antibodies can reach, with medium confidence; UniProt predicts a signal peptide or a membrane-spanning region; its Gene Ontology location is reachable by antibodies, with medium confidence.
Gene: Protein-coding gene on chromosome 11 (7,795,974 to 7,796,942, reverse strand). Ensembl gene ENSG00000183303.
Subcellular location: Cell membrane
Pathways (Reactome):
Sensory Perception: Expression and translocation of olfactory receptors
Gene Ontology:
Molecular function: odorant binding; olfactory receptor activity; G protein-coupled receptor activity
Biological process: sensory perception of smell; detection of chemical stimulus involved in sensory perception of smell; G protein-coupled receptor signaling pathway
Cellular component: plasma membrane; membrane
Genetic constraint (gnomAD): Loss-of-function variants: 3 observed, 1.85 expected, observed/expected ratio (o/e) 1.62, 90% interval 0.59 to 1.93. That is too few expected variants to judge how well the gene tolerates losing a copy. Missense variants: 447 observed, 387.64 expected, observed/expected ratio (o/e) 1.15, 90% interval 1.07 to 1.25. Synonymous variants: 164 observed, 148 expected, observed/expected ratio (o/e) 1.11, 90% interval 0.98 to 1.26.
Homologues: Orthologues: chimpanzee OR5P2 (98% identical), mouse Or5p76 (77% identical), rat Or5p76 (77% identical), rat Or5p76b (76% identical), dog OR5P2 (75% identical), mouse Or5p6 (75% identical), rat Or5p6 (75% identical), mouse Or5p78 (74% identical), rat Or5p78 (74% identical), rat Or5p50 (73% identical), rat Or5p78 (73% identical), rat Or5p69 (73% identical), and 33 more. Paralogues in human: OR5P3 (61% identical), OR5AP2 (49% identical), OR8U3 (48% identical), OR5B12 (48% identical), OR5A1 (47% identical), OR5B21 (47% identical), OR5AR1 (47% identical), OR5F1 (47% identical), OR5M10 (47% identical), OR5M1 (46% identical), OR8D1 (46% identical), OR5A2 (46% identical), and 84 more.